TONSL (tonsoku like, DNA repair protein)
Description:
Component of the MMS22L-TONSL complex, a complex that promotes homologous recombination-mediated repair of double-strand breaks (DSBs) at stalled or collapsed replication forks. The MMS22L-TONSL complex is required to maintain genome integrity during DNA replication. It mediates the assembly of RAD51 filaments on single-stranded DNA (ssDNA): the MMS22L-TONSL complex is recruited to DSBs following histone replacement by histone chaperones and eviction of the replication protein A complex (RPA/RP-A) from DSBs. Following recruitment to DSBs, the TONSL-MMS22L complex promotes recruitment of RAD51 filaments and subsequent homologous recombination. Within the complex, TONSL acts as a histone reader, which recognizes and binds newly synthesized histones following their replacement by histone chaperones. Specifically binds histone H4 lacking methylation at 'Lys-20' (H4K20me0) and histone H3.1.
Synonyms: IKBR; NFKBIL2; SEMDSP
Tractability: PROTAC: ubiquitination databases record sites on it.
Gene: Protein-coding gene on chromosome 8 (144,428,767 to 144,444,473, reverse strand). Ensembl gene ENSG00000160949.
Subcellular location: Nucleus; Chromosome; Cytoplasm
Subcellular location (Human Protein Atlas): Nucleoplasm; Nuclear bodies
Gene Ontology:
Molecular function: histone binding; histone reader activity; protein binding
Biological process: double-strand break repair via homologous recombination; protein localization to chromatin; replication fork processing; chromatin organization
Cellular component: chromosome; DNA replication factor A complex; FACT complex; MCM complex; nuclear body; nuclear replication fork; nucleoplasm; nucleus; site of double-strand break; cytoplasm
Genetic constraint (gnomAD): Loss-of-function variants: 112 observed, 127.9 expected, observed/expected ratio (o/e) 0.88, 90% interval 0.75 to 1.02. The upper end of that interval is the gene's LOEUF score, 1.02, which puts it in group 4 of 6, group 1 being the genes least tolerant of losing a copy. Missense variants: 1,851 observed, 1,715 expected, observed/expected ratio (o/e) 1.08, 90% interval 1.04 to 1.12. Synonymous variants: 849 observed, 733.51 expected, observed/expected ratio (o/e) 1.16, 90% interval 1.09 to 1.23.
Homologues: Orthologues: chimpanzee TONSL (99% identical), macaque TONSL (94% identical), guinea pig TONSL (76% identical), mouse Tonsl (76% identical), rat Tonsl (75% identical), pig TONSL (75% identical), dog TONSL (74% identical), tropical clawed frog tonsl (46% identical), zebrafish tonsl (45% identical), Caenorhabditis elegans mask-1 (22% identical), Drosophila melanogaster mask (11% identical). Paralogues in human: PLA2G6 (10% identical), NFKBIA (7% identical), NFKBIB (7% identical), ANKRD22 (3% identical).
Diseases named in the same sentence as TONSL in open-access papers:
TONSL is named in the same sentence as 17 diseases in open-access papers, as found by Europe PMC text mining. Sharing a sentence is not in itself a finding about the gene and the disease. The quoted sentences say what the papers report.
breast carcinoma (2 papers, 2023 to 2025). "TONSL exhibited the highest hazard ratios among the model genes significantly overexpressed in tumor tissues and was associated with OS in breast cancer patients." (PMID 39944694, 2025). "Interestingly, the Hazardous Ratio was less than 0.5 for the basal type of breast cancer, suggesting that higher expression of TONSL mRNA is associated with better prognosis." (PMID 37298484, 2023). "Higher expression of TONSL mRNA was significantly associated with worse overall survival (OS) in lung adenocarcinoma, gastric cancer (intestinal and diffuse), breast cancer (luminal A, luminal B and HER2-positive) and ovarian cancer (endometrial and serous) (hazard ratios were greater than 1.2)." (PMID 37298484, 2023). "Based on this hypothesis, we questioned the impact of TONSL loss on ovarian cancer, lung cancer, breast cancer, colon cancer and glioblastoma." (PMID 37298484, 2023). "While this manuscript was being revised for publication, a paper was published demonstrating that TONSL is an immortalizing oncogene in breast cancer oncogenesis." (PMID 37298484, 2023). "We also examined recurrence-free survival (RFS) in the same manner, and the pattern of RFS according to the expression of TONSL mRNA was similar to that of OS, except for luminal B breast cancer, which had the opposite result." (PMID 37298484, 2023). "TONSL is located on chromosome 8q24.3, in the region most often amplified in human cancers (up to 40% in breast cancer) and adjacent to the strong oncogenic driver MYC (c-myc), which is located at 8q24.2." (PMID 37298484, 2023). "Molecular assays were performed to investigate the role of the key gene TONSL in breast cancer." (PMID 39944694, 2025). "TONSL may serve as a potential therapeutic target for breast cancer, particularly in triple-negative breast cancer, indicating new treatment strategies for these patients." (PMID 39944694, 2025).
triple-negative breast carcinoma (2 papers, 2025). An invasive breast carcinoma which is negative for expression of estrogen receptor (ER), progesterone receptor (PR), and human epidermal growth factor receptor 2 (HER2). "Furthermore, single-cell analysis revealed elevated TONSL expression in dendritic and epithelial cells, particularly in triple-negative breast cancers." (PMID 39944694, 2025). "Collectively, these findings indicate that candidate genes including TONSL may represent potential therapeutic targets for triple-negative breast cancer." (PMID 41179682, 2025).
cervical cancer (1 paper, 2023). A primary or metastatic malignant neoplasm involving the cervix. "This module's four proteins, MCM2, MCM10, POLA1, and TONSL, are cervical cancer driver genes based on the DriverDBv3 report." (PMID 37746664, 2023). "The logFC values of the MCM2, MCM10, POLA1, and TONSL in cervical cancer versus normal groups are 2.3, 3.37, 1.76, and 0.587, respectively." (PMID 37746664, 2023). "TONSL was introduced as an oncogene in esophageal, lung, and cervical cancers." (PMID 37746664, 2023).
colon cancer (1 paper, 2023). "In addition, the loss of TONSL resulted in selective depletion of CSCs in the tested cell lines, including colon cancer, ovarian cancer and glioblastoma lines." (PMID 37298484, 2023). "We also found that TONSL is required for CSCs in glioblastoma (U87MG and LN229) and colon cancer (HCT15 and HT29)." (PMID 37298484, 2023). "In the colon cancer cell HT29, the siRNA targeting TONSL increased the expression of G2/M cyclins (Cyclin B and Cyclin A) in both cell groups (BCC and CSC)." (PMID 37298484, 2023).
colorectal cancer (1 paper, 2024). A primary or metastatic malignant neoplasm that affects the colon or rectum. "However, there is no information on the role of NAP1L2, TONSL, HDAC9, and CHAF1B in colorectal cancer and were selected for further verification by qRT-PCR." (PMID 38212708, 2024).
dysplasia (1 paper, 2021). A usually neoplastic transformation of the cell, associated with altered architectural tissue patterns. "Knockdown of TONSL by siRNA treatment in patient cells from SPONASTRIME dysplasia, a rare weak bone disease caused by hypomorphic mutation of TONSL, reduces RAD51 foci upon CPT treatment, revealing its essential role in RAD51’s ability to load to DNA damage sites by interacting with RPA." (PMID 33498235, 2021).
Fanconi anemia (1 paper, 2025). Fanconi anemia (FA) is a hereditary DNA repair disorder characterized by progressive pancytopenia with bone marrow failure, variable congenital malformations and predisposition to develop hematological or solid tumors. "Previous studies have highlighted TONSL’s role in promoting tumorigenesis, with its overexpression upregulates DNA repair-related genes in pathways such as HR and Fanconi anemia, conferring resistance to damage." (PMID 39944694, 2025). "TONSL knockdown significantly reduced the expression of FANCD1 and XRCC2, both key players in the Fanconi anemia and homologous recombination repair pathways, while DDB2 and NEIL3 showed no statistically changes." (PMID 39944694, 2025).
lung adenocarcinoma (1 paper, 2023). A carcinoma that arises from the lung and is characterized by the presence of malignant glandular epithelial cells. "Overall, higher expression in tumor tissue was associated with longer survival in lung adenocarcinomas, which was the opposite effect to that of TONSL." (PMID 37298484, 2023). "As with TONSL, several HRR mediators at the fork are also associated with poor prognosis in lung adenocarcinoma." (PMID 37298484, 2023).
ovarian carcinoma (1 paper, 2023). A malignant neoplasm originating from the surface ovarian epithelium. "In ovarian cancers, 1/3 of the TONSL-amplified tissues expressed higher TONSL mRNA (of 32% of tumors with TONSL gene amplification, only 12% highly expressed TONSL mRNA)." (PMID 37298484, 2023). "Accordingly, we sought to determine why amplification of the TONSL gene frequently occurs in ovarian cancer, and its impact." (PMID 37298484, 2023). "However, senescence increased dramatically in TONSL-depleted CSCs, suggesting that senescence is the main mechanism eliminating the CSC population in these ovarian cancer cells and can be different from the mechanism of BCC loss." (PMID 37298484, 2023). "Among those, more than 25% of ovarian cancers harbored gene amplification of TONSL." (PMID 37298484, 2023). "We also confirmed that γH2AX was increased by the suppression of TONSL in ovarian cancers." (PMID 37298484, 2023). "TONSL was expressed at higher levels in cancer tissues than in normal tissues, and higher expression was an unfavorable prognostic marker for lung, stomach, breast and ovarian cancers." (PMID 37298484, 2023).
tumor (9 papers, 2021 to 2026). "This study found that TONSL is often overexpressed in tumor tissues and is linked to a poor prognosis." (PMID 42002539, 2026). "TONSL expression can impact immune infiltration in the tumor microenvironment and subsequently affect tumor prognosis." (PMID 42002539, 2026). "In the mouse xenograft tumor models, tumors with reduced TONSL expression showed an improved response to carboplatin, resulting in smaller tumor sizes compared to the control group." (PMID 39944694, 2025). "In summary, TONSL plays a significant role in tumor resistance to DNA-damaging drugs, potentially participating in the regulation of the immune microenvironment." (PMID 39944694, 2025). "Intersection of these gene sets yielded four high-confidence tumor dependency genes (TONSL, TIMELESS, RFC3, RAD51) for further investigation." (PMID 41179682, 2025). "We also performed single-cell analysis to determine the expression of TONSL in the tumor immune microenvironment." (PMID 39944694, 2025). "In summary, RAD51, TIMELESS, RFC3, and TONSL converge on pro-proliferative pathways that sustain tumor survival and expansion." (PMID 41179682, 2025). "In 3 PDX models from the responder group without BRCA1/2 mutations or BRCA1 promoter methylation, we identified mutations in the DDR genes XRCC3 (HBCx-14), TONSL (HBCx-33) and ORC1 (T302), that were present also in the matched patients’ primary tumours." (PMID 37029129, 2023). "This study only preliminarily confirmed the effect of TONSL on the phenotype of tumor cells." (PMID 41179682, 2025). "In conclusion, we showed the promising activity of TFDC-based immunotherapy in IDH-WT GBM and the association of low HLA-A expression and the absence of CCDC88A, KRT4, TACC2, and TONSL mutations in tumor cells of patients showing better prognosis." (PMID 37382632, 2023). "Interestingly, it has been noted that the TONSL gene is amplified in several cancers, suggesting an oncogenic role different from those of other well-studied tumor-suppressive HRR genes in cancer or carcinogenesis." (PMID 37298484, 2023). "Low HLA-A expression and lack of CCDC88A, KRT4, TACC2, and TONSL mutations in tumor cells were correlated with better prognosis." (PMID 37382632, 2023). "TONSL variants were observed in 5/14 (36%) patients, all of which belonged to the high HLA-A expression group, as determined by NGS; the presence of a TONSL mutation was significantly associated with high HLA-A expression in tumor cells." (PMID 37382632, 2023). "Its overexpression in multiple cancer types implies that these cancer cells may be dependent on TONSL for survival, and inhibiting its function may be detrimental to tumor growth." (PMID 33498235, 2021). "The analysis of showed that PHF19, AURKA, CHAF1B and AURKB were up-regulated in the tumor group, NAP1L2, TONSL, SATB2 and HDAC9 were down-regulated in the tumor group." (PMID 38212708, 2024). "Among them, PHF19, AURKA, CHAF1B and AURKB were up-regulated in the tumor group, NAP1L2, TONSL, SATB2 and HDAC9 were down-regulated in the tumor group." (PMID 38212708, 2024). "Notably, TONSL, TIMELESS, RFC3, and RAD51 exhibited significantly higher expression levels within the tumor regions compared to the tumor stromal areas, suggesting their predominant role in tumor cells." (PMID 41179682, 2025). "Overall, our study identifies TONSL, TIMELESS, RFC3, and RAD51 as tumor dependency genes." (PMID 41179682, 2025).
cancer (8 papers, 2018 to 2026). A tumor composed of atypical neoplastic, often pleomorphic cells that invade other tissues. "Conversely, elevated expression of the essential HRR gene TONSL in cancer versus normal tissues and its association with poor prognosis in many major cancer types is distinguished from the characteristics of many other HRR gene alterations." (PMID 37298484, 2023). "Cancer stem cell (CSC)-enriched cultures and bulk/general mixed cell cultures (BCCs) with RNAi were employed to determine the effect of TONSL loss in cancer cell lines from the ovary, breast, stomach, lung, colon and brain." (PMID 37298484, 2023). "The association of TONSL mRNA expression with the survival of cancer patients was analyzed via the KM plotter online tool." (PMID 37298484, 2023). "It has been reported that TONSL is overexpressed in hepatocellular carcinoma, and it is implicated in the carcinogenesis of several cancers including lung and esophageal cancer." (PMID 33498235, 2021). "If CHK1 is inhibited in combination with TONSL inhibition, it will increase DNA damage and replication stress causing the cell cycle to bypass into mitosis, further burdening the cancer cells." (PMID 33498235, 2021). "In addition, the MMS22L mutation pattern, which is rarely amplified in cancer, should be considered when evaluating the significance of the oncogenic role of TONSL." (PMID 37298484, 2023). "Another reason TONSL may be an attractive target for cancer drug development is due to the different mutation profile and pathway reliance." (PMID 33498235, 2021). "One potential strategy is inhibiting TONSL in BRCA1/2 deficient cancer, similar to PARPi." (PMID 33498235, 2021). "The inventors mention that mutation in the ARD domain was identified in multiple cancers types, indicating that this region may be critical for TONSL’s function." (PMID 33498235, 2021). "In cancers, this HR function of TONSL has been identified as essential for maintaining cancer stem cell (CSC) properties." (PMID 41179682, 2025). "Chromosome 8q is one of the most amplified segments in cancer, and the gene TONSL, which is located on the same arm, is also amplified in many cancers." (PMID 37298484, 2023). "We demonstrate that TONSL is enriched in cancer tissues versus normal tissues and that higher expression is associated with worse prognosis." (PMID 37298484, 2023). "The results of the present study will further increase the understanding of the role of TONSL in cancer stem cells specifically and provide a rationale for targeting TONSL to treat cancer." (PMID 37298484, 2023). "In this study, we identified that the gene of a replication fork HRR mediator, TONSL, is amplified and transcriptionally upregulated in several cancers." (PMID 37298484, 2023). "Although the TONSL complex is yet to be tested as a target for cancer therapy, the development possibilities are bright." (PMID 33498235, 2021). "Although experimentally not yet shown, there is the possibility of synthetic lethality of TONSL inhibition in HR-defective or replication stressed cancer cells, similar to other compounds discussed in this paper." (PMID 33498235, 2021). "In this study, we investigated whether the TONSL gene plays an important role in cancer and CSCs using RNAi and CSC enrichment cultures in addition to bioinformatics analyses of various public databases." (PMID 37298484, 2023). "Interestingly, more than 5% of the tumors from all of the examined cancer tissues showed greater TONSL gene amplification." (PMID 37298484, 2023). "Interestingly, amplification of PKHD1L1 and other genes at a similar distance from MYC but in the opposite direction from TONSL was observed in only 60% of MYC-amplified cancers." (PMID 37298484, 2023). "Because we previously noted that GBM CSCs are more vulnerable to the loss of TONSL than bulk cultured cells (BCCs), we investigated whether TONSL plays an important role in cancer prognosis in other cancers." (PMID 37298484, 2023).
cancer (continued). "Because this finding suggests pro-cancer roles of TONSL expression, we questioned whether the expression of TONSL increases in cancer." (PMID 37298484, 2023). "In this review, we present TONSL as a potential novel target for cancer therapy." (PMID 33498235, 2021). "Here, we suggest the possibility of TONSL as a novel cancer therapeutic target." (PMID 33498235, 2021). "The previous finding that TONSL may be essential in CSCs was demonstrated again in several cancers." (PMID 37298484, 2023). "Studies of TONSL have shown that downregulating it clearly decreases cell survival and increases drug sensitivity to DNA damaging agents, implying that it may lead to cell death in the context of cancer." (PMID 33498235, 2021). "Experimental data implies targeting TONSL may be effective for cancer therapy." (PMID 33498235, 2021). "We investigated the role of TONSL, a mediator of homologous recombination repair (HRR), in stalled replication fork double-strand breaks (DSBs) in cancer." (PMID 37298484, 2023). "As TONSL-mediated HRR in the replication fork is essential, to preserve genome integrity in the repair process, the requirement of TONSL should be the same in all cancer cells." (PMID 37298484, 2023). "MtrBTN2 cancer was found to express at higher levels a significant panel of transcripts of genes involved in the DNA homologous recombination (HR) (42.Double-strand break repair), such as BABAM1, ZSWIM7, RAD51L, RAD54L, MRE11, MCM9 and TONSL." (PMID 37816387, 2023). "To date, no studies have been conducted supporting the non-oncogenic addiction to TONSL in cancer cells, nor its efficacy as a target protein for cancer therapy." (PMID 33498235, 2021). "The suppression of TONSL using RNAi revealed that it is required in the survival of CSCs in cancer cells, while BCCs could frequently survive without TONSL." (PMID 37298484, 2023).
TONSL also shares sentences with these, for which no sentence is quoted: bacterial disease (1 paper); gastric cancer (1); glioblastoma (1); lung carcinoma (1); ovarian serous adenocarcinoma (1); prostate carcinoma (1).